CABP5 (calcium binding protein 5)
Description:
Inhibits calcium-dependent inactivation of L-type calcium channel and shifts voltage dependence of activation to more depolarized membrane potentials (By similarity). Involved in the transmission of light signals (By similarity). May positively regulate neurotransmitter vesicle endocytosis and exocytosis in a salt-dependent manner (By similarity). May play a role in the extension and network organization of neurites (By similarity).
Synonyms: CABP3
Tractability: No criterion of Open Targets' tractability assessment is met for any kind of drug.
Gene: Protein-coding gene on chromosome 19 (48,029,383 to 48,044,079, reverse strand). Ensembl gene ENSG00000105507.
Subcellular location: Cytoplasm
Gene Ontology:
Molecular function: protein binding; calcium channel regulator activity; calcium ion binding
Biological process: phototransduction; signal transduction; visual perception
Cellular component: cytosol; cytoplasm
Genetic constraint (gnomAD): Loss-of-function variants: 17 observed, 18.85 expected, observed/expected ratio (o/e) 0.9, 90% interval 0.62 to 1.35. The upper end of that interval is the gene's LOEUF score, 1.35, which puts it in group 5 of 6, group 1 being the genes least tolerant of losing a copy. Missense variants: 229 observed, 229.59 expected, observed/expected ratio (o/e) 1, 90% interval 0.89 to 1.11. Synonymous variants: 85 observed, 78.09 expected, observed/expected ratio (o/e) 1.09, 90% interval 0.91 to 1.3.
Homologues: Orthologues: chimpanzee CABP5 (99% identical), dog CABP5 (97% identical), rabbit CABP5 (95% identical), guinea pig CABP5 (94% identical), mouse Cabp5 (93% identical), rat Cabp5 (90% identical), pig CABP5 (87% identical), zebrafish cabp5a (75% identical), zebrafish cabp5b (71% identical), Caenorhabditis elegans cal-1 (35% identical), Caenorhabditis elegans cal-3 (34% identical), Drosophila melanogaster CG30378 (29% identical), and 9 more. Paralogues in human: CABP2 (65% identical), CABP1 (65% identical), CABP4 (55% identical), CALM1 (38% identical), CALM2 (38% identical), CALM3 (38% identical), CABP7 (36% identical), CALML3 (36% identical), CALN1 (36% identical), CETN2 (31% identical), CALML6 (31% identical), CETN1 (31% identical), and 8 more.
Diseases named in the same sentence as CABP5 in open-access papers:
CABP5 is named in the same sentence as 7 diseases in open-access papers, as found by Europe PMC text mining. Sharing a sentence is not in itself a finding about the gene and the disease. The quoted sentences say what the papers report.
irritable bowel syndrome (1 paper, 2020). Irritable bowel syndrome (IBS) is a chronic functional condition of the lower gastrointestinal (GI) tract characterized by abdominal pain or discomfort and disordered bowel habit (diarrhea, constipation, or fluctuation between the two). "Additionally, several strong associations of irritable bowel syndrome (IBS) and digestive disorders with loci in CABP5 are shown." (PMID 31888951, 2020).
Obesity (1 paper, 2020). Accumulation of substantial excess body fat. "We also identified SNPs in two genes, PFKFB3 and CABP5, which are associated with obesity in other studies." (PMID 31888951, 2020).
CABP5 also shares sentences with these, for which no sentence is quoted: cancer (1 paper); gastric cancer (1); lung carcinoma (1); medulloblastoma (1); tumor (1).